FLOT2 (flotillin 2)
Diseases named in the same sentence as FLOT2 in open-access papers (continued):
Sharing a sentence is not in itself a finding about the gene and the disease.
gestational diabetes mellitus (2 papers, 2019 to 2022). "Gestational diabetes mellitus mice exhibited IR and liver gluconeogenesis, up‐regulated FLOT2, activated PI3K/AKT pathway and down‐regulated miR‐351 in liver tissues." (PMID 31287224, 2019). "In addition, a study on gestational diabetes mellitus showed that the phosphatidylinositol-3-kinase and protein kinase B pathway could be repressed by regulating FLOT2 expression, suggesting FLOT2 inhibition could alleviate insulin resistance and liver gluconeogenesis." (PMID 35692841, 2022).
head and neck squamous cell carcinoma (2 papers, 2024 to 2025). A squamous cell carcinoma that arises from any of the following anatomic sites: lip and oral cavity, nasal cavity, paranasal sinuses, pharynx, larynx, and salivary glands. "miR-34a-5p suppresses Head and Neck Squamous Cell Carcinoma (HNSCC) by targeting flotillin 2 (FLOT-2) which is associated with cancer progression." (PMID 40061926, 2025).
neuropathy (2 papers, 2015 to 2019). A disorder affecting the nervous system that manifests with pain, tingling, numbness, and/or muscle weakness. "Notably, FLOT1 and FLOT2 were markedly depleted in RTX neuropathy associated with TRPV1(+) neuronal depletion." (PMID 30578250, 2019). "Recently, in neuropathy, it was also suggested that Flot2 was involved in Src activation, which is known as the downstream signal of TGF-β." (PMID 25909165, 2015).
non-small cell lung carcinoma (2 papers, 2014 to 2015). A group of at least three distinct histological types of lung cancer, including non-small cell squamous cell carcinoma, adenocarcinoma, and large cell carcinoma. "In this study, we have investigated the correlation between the expression of Flot-2 and EGFR, which increase significantly in non-small cell lung cancer (NSCLC) patients (n=352) compared with non-cancer tissues." (PMID 26161893, 2015).
acute myeloid leukemia (1 paper, 2023). Acute myeloid leukemia (AML) is a group of neoplasms arising from precursor cells committed to the myeloid cell-line differentiation. "Depletion of Flot2 demonstrated its essential role in CD44 expression, but its absence affects the cytoskeleton, polarity, and homing defects, as well as the progression of chronic myeloid leukemia (CML), while acute myeloid leukemia (AML) remains unaffected." (PMID 37795089, 2023).
amyloid (1 paper, 2014). "In brain from flotillin 1-/- and flotillin 1-/-, flotillin 2-/- mice expressing the APPPS1 transgenes we observed less Aβ and less amyloid plaques, as compared with controls." (PMID 24465508, 2014).
autism (1 paper, 2020). Persistent deficits in social interaction and communication and interaction as well as a markedly restricted repertoire of activity and interest as well as repetitive patterns of behavior. "Similarly, FLOT2, which was associated with intelligence (p = 3.97 × 10−05), encodes neuronal signaling factor flotillin-2, and it has been linked previously with autism and related disorders." (PMID 32413284, 2020).
cystic kidney disease (1 paper, 2012). A congenital or acquired kidney disorder characterized by the presence of renal cysts. "Analyses indicated 13 genes, in addition to Nek8 and Ift20 within this area that could potentially result in cystic kidney disease, namely: RGD1309077Phf12, Flot2, Spag5, Sdf2, Supt6h, Proca1, Traf4, Sarm1, Nlk and Ksr1." (PMID 22899815, 2012).
Fabry disease (1 paper, 2020). Fabry disease (FD) is a progressive, inherited, multisystemic lysosomal storage disease characterized by specific neurological, cutaneous, renal, cardiovascular, cochleo-vestibular and cerebrovascular manifestations. "Alterations in the flotillin 2 distribution indicate that the membrane and in particular the organization and function of lipids rafts are altered, as has also been shown in other lysosomal storage diseases, namely Fabry disease." (PMID 32252429, 2020).
glomerular disease (1 paper, 2023). "We found that Flot2 was widely downregulated in glomerular podocytes from patients with different glomerular diseases, and also in cultured podocytes in response to injury stimulation." (PMID 36632460, 2023). "Flot2 was also downregulated in renal biopsies from patients with proteinuric glomerular diseases, including MCD, FSGS, IgAN, MN, and DN." (PMID 36632460, 2023). "We also demonstrated that Flot2 protein expression was positively correlated with eGFR and negatively correlated with proteinuria in proteinuric glomerular diseases." (PMID 36632460, 2023). "Flot2 was thus required to recruit SD proteins into rafts, and mediated podocyte injury and proteinuric glomerular disease." (PMID 36632460, 2023).
GM1 gangliosidosis (1 paper, 2020). A rare lysosomal storage disorder characterized biochemically by deficient beta-galactosidase activity and clinically by a wide range of variable neurovisceral, ophthalmological and dysmorphic features. "Interestingly, a significant shift in the location of flotillin 2 towards fractions 2 and 3 revealed a redistribution of flotillin-2 in the lipid raft fractions of GM1-gangliosidosis cells." (PMID 32252429, 2020).
Hyperglycemia (1 paper, 2025). An increased concentration of glucose in the blood. "Hyperglycemia also upregulates FLOT2 and downregulates ITGA3 via ROS and TGF-β1-dependent epigenetic remodeling of their gene promoters, reducing integrin-mediated podocyte adhesion and actin stability." (PMID 41368354, 2025).
insomnia (1 paper, 2020). A sleep disorder characterized by difficulty in falling asleep and/or remaining asleep. "Two examples of this include FLOT2 (p = 3.97 × 10−05 with intelligence), which encodes the neuronal signaling factor flotillin-2, and SIDT1 (p = 1.34 × 10−05 with insomnia), which is a dsRNA transporter." (PMID 32413284, 2020).
lung carcinoma (1 paper, 2015). "Signal transduction through epidermal growth factor receptors (EGFR) and Flot-2 play an important role in cancer development, but their precise role in lung cancer has not been investigated." (PMID 26161893, 2015).
lysosomal storage disease (1 paper, 2020). A metabolic disorder caused by mutations in proteins critical for lysosomal function, including lysosomal enzymes, lysosomal integral membrane proteins, and proteins involved in the post-translational modification and trafficking of lysosomal proteins. "Flotillin 2 is a highly conserved protein isolated from caveolae/lipid raft domains responsible for signaling and trafficking of molecules within a cell, and abnormalities have been attributed to the pathophysiology in several lysosomal storage diseases." (PMID 32252429, 2020).
medulloblastoma (1 paper, 2025). A malignant, invasive embryonal neoplasm arising from the cerebellum. "Proteins commonly found in exosomes and microvesicles, namely, CD63, Alix, Flotillin-2 and TSG101, were present in EVs isolated from both non-treated and cisplatin-treated SHH and group 3 medulloblastoma cells and their corresponding whole cell extracts." (PMID 40495204, 2025).
Nephropathy (1 paper, 2023). A nonspecific term referring to disease or damage of the kidneys. "Flot2 expression in the kidney was also reduced in diabetic db/db mice, and in lipopolysaccharide (LPS)- induced and adriamycin (ADR)-induced nephropathy mice, as shown by double immunostaining of Flot2 and synaptopodin." (PMID 36632460, 2023). "We first confirmed that Flot2 was expressed in podocyte and demenstrated that podocyte-specific Flot2 deletion worsen albuminuria, podocyte injury and glomerular pathology in LPS/ADR-induced nephropathy mouse models." (PMID 36632460, 2023). "Podocyte-specific Flot2-deletion worsened albuminuria, podocyte injury, and glomerular pathology in LPS- and ADR-induced nephropathy mouse models." (PMID 36632460, 2023). "Podocyte-specific Flot2 deletion exacerbated albuminuria, podocyte injury, and glomerular pathology in LPS- and ADR-induced nephropathy mouse models." (PMID 36632460, 2023).
promyelocytic leukemia (1 paper, 2019). "Expression levels of FLOT1 and FLOT2 during A. phagocytophilum infection in human promyelocytic leukemia (HL-60) and monkey endothelial (RF/6A) cell lines were measured by quantitative reverse transcription-PCR (qRT-PCR) and Western blotting." (PMID 30914515, 2019).
renal carcinoma (1 paper, 2023). A carcinoma arising from the epithelium of the renal parenchyma or the renal pelvis. "We further assessed the expression of Flot2 in renal biopsies from patients with MCD (n=7), FSGS (n=8), MN (n=8), IgAN (n=5), and DN (n=6) compared with normal renal tissues from subjects with renal carcinoma (n=3) by immunohistochemistry (IHC)." (PMID 36632460, 2023).
renal fibrosis (1 paper, 2025). A final common manifestation of a wide variety of chronic kidney diseases characterized by glomerulosclerosis and tubulointerstitial fibrosis. "Methodologically, the CRISPR/Cas9-mediated knockout technique was used in a Chinese study where Flot2 expression was significantly altered in mouse models of renal fibrosis and glomerular injury." (PMID 41368354, 2025).
schizophrenia (1 paper, 2024). A major psychotic disorder characterized by abnormalities in the perception or expression of reality. "Variants in FOXN1 and FLOT2 would have been categorized as damaging from recent schizophrenia and bipolar exome sequencing studies." (PMID 39080272, 2024).
Sepsis (1 paper, 2022). Sepsis is defined as life-threatening organ dysfunction caused by a dysregulated host response to infection. "Compared to the controls, the patients with sepsis consistently showed significant isoform switching of the FLOT2, LRG1 and MEGF9 genes." (PMID 35715539, 2022). "In our study, we found that FLOT2 abundance was significantly increased in the patients with sepsis compared to the controls." (PMID 35715539, 2022).
ZIKV infection (1 paper, 2018). "Quantification of Flotillin-2 in EVs against β-actin in WCL identified that ZIKV infection dramatically increased the levels of Flotillin-2 and Alix in the EV lysates, confirming that ZIKV infection increases EV biogenesis in astrocytes." (PMID 29707233, 2018).
cancer (37 papers, 2013 to 2026). A tumor composed of atypical neoplastic, often pleomorphic cells that invade other tissues. "Flotillin-1 and flotillin-2 are frequently overexpressed in cancers and are associated with poor survival." (PMID 29642469, 2018). "Deregulated FLOT2 is associated with progression and poor survival in numerous types of cancer, making it a critical regulator of tumor initiation and prognosis." (PMID 26576674, 2015). "FLOT2 is an oncogene involved in the pathogenic process of several cancers." (PMID 35692841, 2022). "Also, flotillin-2 (FLOT2), a member of the flotillin family, has been shown to be upregulated in many cancers and is associated with cancer progression." (PMID 33817236, 2020). "Furthermore, this active fraction decreased Flotillin-2 expression associated with cancer progression." (PMID 32922490, 2020). "However, the underlying mechanism for Flot2 promoting metastasis in cancer cells was still unclear." (PMID 25909165, 2015). "FLOT2 interacts with HER2 and positively regulates HER2 activation and downstream signaling, while FLOT2 knockdown reduces the viability of HER2 amplified cancer cells." (PMID 42239129, 2026). "The activity of the pathway is counter-proportionally correlated with cancer-related proteins, like flotillin 2 (FLOT2) or early growth response 2 (EGR2)." (PMID 39188680, 2024). "As an important regulator of oncogenic signaling, FLOT2 participates in the development of cancer via PI3K/AKT/MAPK, PI3K/AKT/mTOR, PI3K/AKT/FOXO and NF-κB signaling pathways." (PMID 38285090, 2024). "It has been reported that FLOT2 participates in the development of several types of malignant tumors, which activates the PI3K/AKT/mTOR, PI3K/AKT/MAPK pathways and NF-κB signaling to promote cell proliferation, migration and invasion." (PMID 38285090, 2024). "FLOT2 has been shown to assume a pivotal role in cancer cell proliferation, invasion, and migration, underscoring its significance in the progression of malignant diseases." (PMID 38052924, 2023). "It has been established that flotillin-2 (FLOT2) has a critical role in the progression of human cancers through different mechanisms." (PMID 35715800, 2022). "Together, these data highlight miR-34a-5p/FLOT-2 axis as a viable therapeutic target for this cancer type." (PMID 34803501, 2021). "Immunostaining showed that FLOT2 expression was markedly increased in cancer tissues of SCLC patients." (PMID 30836864, 2019). "Curiously, only few papers describe the presence of flotillin-2 within the nuclei of cancer cells, and therefore nuclear flotillin-2 cannot be described as a characteristic of all cancer cell types or specific to breast tumor cancer cells." (PMID 31562347, 2019). "Flotillin-2 (Flot2), a specialized lipid raft domain in cellular membrane, was reported to promote cancer metastasis." (PMID 25909165, 2015). "Interaction has been found between Flotillins and EGFR in cancer cells and Flot-2 becomes Tyr- phosphorylated by Src kinase based on EGFR activation." (PMID 26161893, 2015). "Flotillin-2 (Flot2), a member from flotillin family, is a marker of lipid rafts and reported to play key roles in the development and progression of human malignant tumors." (PMID 26576674, 2015). "In this study, we found that Flot2 expression level positively correlated with the cancer stage in NPC tissues." (PMID 25909165, 2015). "FLOT2 is a proto-oncogene that regulates cell migration and invasion in cancer." (PMID 34059086, 2021). "Moreover, a decrease in the expression of FLOT2, which is generally over-expressed in cancer cells, has been observed." (PMID 32922490, 2020). "FLOT2 is a lipid raft marker which promotes the progression of several types of cancer." (PMID 32922490, 2020). "It is known that FLOT2 is upregulated in several types of cancer, including SCLC." (PMID 30836864, 2019). "FLOT2 is important for non-caveolar raft formation and associated with the development and progression of cancer." (PMID 30836864, 2019).
cancer (continued). "Flotillin-2 is one of the membrane raft markers involved in cancer progression." (PMID 31477154, 2019). "FLOT2 is a major protein on lipid rafts, important for non-caveolar raft formation and associated with the development and progression of cancer." (PMID 30836864, 2019). "Additionally, target gene expression level in the cancer EC was compared to flotillin-2 expression, in order to ensure that genes were expressed at a high enough level to be of interest." (PMID 26943033, 2016). "Given the role of lipid rafts in a number of cellular mechanisms that are dysregulated in tumor cells, such as altered protein signaling and trafficking, it is possible that abnormalities of FLOT2 protein contribute to the formation of cancer-specific cellular characteristics." (PMID 23945257, 2013). "It is reported that FLOT2 could activate the NF-κB signaling to promote cancer development." (PMID 38285090, 2024). "Thus, besides directly interfering with the Wnt signalling pathway, regulating Flot2-mediated Wnt cytonemes in the cancer stem cell niche could provide a novel strategy for combatting Wnt-related cancers." (PMID 36040316, 2022). "To evaluate the functional importance of FLOT-2 in HNSCC, we next evaluated the expression of this protein in this cancer type using the TCGA database, categorizing HNSCC tissues into FLOT-2-high or -low samples based on immunostaining scores." (PMID 34803501, 2021). "Inversely, knocking down either FLOT1 or FLOT2 almost completely blocked the enhanced aggressiveness of heat-treated HCCLM3 cells in vitro and of residual cancer after insufficient RFA in vivo." (PMID 30820716, 2019). "In accordance with studies in other cancers, knocking down FLOT1 and/or FLOT2 inhibited the invasion, migration, and anchorage-independent growth of HCCLM3 cells in vitro and decreased their tumor growth and metastasis in vivo." (PMID 30820716, 2019). "Gene expression was normalised to both flotillin-2 (per cell expression level) and PECAM-1 (per endothelial cell expression level) in order to assess the level of enrichment of the target in the cancer endothelium." (PMID 26943033, 2016). "In addition to these regulatory interactions, miR-802 downregulates the expression of flotillin-2 (FLOT2), a protein that has been described as a promoter of tumor growth in various types of cancer." (PMID 40564936, 2025). "FLOT-2 Promotes the proliferation and EMT of cancer cells by activating the MEK/ERK1/2 pathway." (PMID 40061926, 2025). "In addition, the frequency of FLOT1, FLOT2, and TSG101 proteins was higher in cancer cell-line-derived exosomes when compared to control cell-line-derived exosomes." (PMID 38529947, 2024). "Moreover, in addition to Lin28B there are several putative cancer stem cell markers, such as MUC1, CD38, FLOT2, EGF and IKBKB that were also upregulated (signal log2 ratio>0.5) in mH2A1-depleted LD611 cells." (PMID 26028027, 2016). "Although most studies on flotillins in cancer have described an elevated flotillin-2 expression, most of them did not address flotillin-1 directly or found that flotillin-1 expression has no predictive value in terms of e.g. patient survival." (PMID 24304721, 2013). "In other words, Flot2 elevation is not the compensative result of EMT or cancer metastasis." (PMID 25909165, 2015). "In contract with previous studies that silencing Flot2 could suppress the metastatic capacity of some cancer cells, our experiments demonstrated that simply silencing Flot2 without any other stimuli was not sufficient to change either cell motility or EMT marker expressions." (PMID 25909165, 2015). "Given the divergence of Flot2 in NPC and other cancers, we speculated that metastatic regulating network is not complete the same in all cancers, and NPC Flot2 may be a special case." (PMID 25909165, 2015).